CHI3L1 (chitinase 3 like 1)
Diseases named in the same sentence as CHI3L1 in open-access papers (continued):
Sharing a sentence is not in itself a finding about the gene and the disease.
colorectal cancer (48 papers, 1999 to 2026). A primary or metastatic malignant neoplasm that affects the colon or rectum. "Recent studies have shown that CHI3L1 is highly expressed in solid tumors, including lung cancer, breast cancer, and colorectal cancer, and is closely associated with tumor invasiveness, chemotherapy resistance, and poor prognosis." (PMID 40260255, 2025). "Evaluation and analysis of various biomarkers’ clinical potential in colorectal cancer patients have revealed that CHI3L1 demonstrates a higher diagnostic value compared to mature miRNA levels in serum (miRNA-576-3p, miRNA-613) and serum NDRG2 levels." (PMID 38003338, 2023). "Moreover, the D299G mutation is associated with higher tumor grades and increased metastasis rates, underscoring the pivotal role of TLR4 mutations and CHI3L1 upregulation in colorectal cancer development and progression." (PMID 40260255, 2025). "In colorectal cancer, cancer-associated fibroblasts secrete CHI3L1 to regulate tumor angiogenesis." (PMID 37958973, 2023). "For example, in colorectal cancer, CHI3L1 expression has been shown to correlate with MAPK activation and poor clinical outcomes, and its overexpression significantly increases tumor growth and vascularization in xenograft models." (PMID 40643503, 2025). "Studies have demonstrated that stimulation with the TLR4 ligand LPS downregulates CHI3L1 expression in SW480 colorectal cancer cells." (PMID 40260255, 2025). "We investigated the relationship between CHI3L1 and colorectal cancer using the Open Targets Platform." (PMID 38177294, 2024). "Conversely, the knockdown of CHI3L1 by RNA interference or neutralization by an anti-CHI3L1 antibody strongly suppressed the CHI3L1-induced migration and tube formation of human colorectal cancer cells." (PMID 38177294, 2024). "CHI3L1 is significantly upregulated in patients with colorectal cancer compared with healthy individuals." (PMID 38177294, 2024). "Chitinase-3-like 1 overexpression in colorectal cancer cells in vitro was shown to upregulate IL-8 secretion and activate Erk1/2 and JNK." (PMID 39200479, 2024). "The overall association scores of CHI3L1, EGFR and VEGF with colorectal cancer were 0.079, 0.555, and 0.596, respectively." (PMID 38177294, 2024). "CHI3L1 is upregulated in colon tumor tissues and has been proposed as a potential biomarker of colorectal cancer." (PMID 38177294, 2024). "The putative target proteins of CHI3L1 in colorectal cancer are involved in diverse biological processes related to the development and progression of the disease." (PMID 38177294, 2024). "CHI3L1 has been proposed both as a biomarker and a potential therapeutic target in gastric and colorectal cancer, being overexpressed in serum and tumor tissue being involved in promoting cancer cell proliferation, invasion and metastasis." (PMID 33846436, 2021). "Consistent with our finding, a previous study suggests that CHI3L1 promotes macrophage recruitment in colorectal cancer." (PMID 34612767, 2021). "Additionally, serum CHI3L1 levels have been shown to correlate with poor prognosis, metastatic potential, and treatment response in colorectal cancer patients." (PMID 40643503, 2025). "A better understanding of CHI3L1 kinetics and function in distinct clinical contexts, such as chronic inflammation versus sporadic colorectal cancer, may help define its utility as a context-specific biomarker." (PMID 40643503, 2025). "CHI3L1 also regulates the expression of proinflammatory cytokines in colorectal cancer." (PMID 38177294, 2024). "Therefore, further research on the development of drugs targeting CHI3L1 in colorectal cancer is necessary." (PMID 38177294, 2024). "Moreover, overexpressing CHI3L1 in colorectal cancer cells was shown to enhance colon tumor growth in mice." (PMID 38177294, 2024). "Next, we analyzed the target proteins of CHI3L1 in colorectal cancer." (PMID 38177294, 2024).
colorectal cancer (continued). "Therefore, for early diagnosis of colorectal cancer, the combination of CHI3L1 with other markers is usually required to improve accuracy." (PMID 38003338, 2023). "Additionally, in the setting of colorectal cancer, CHI3L1 showed to be crucial for the maximal enhancement of inflammatory chemotaxis mediated by the release of IL-8 and MCP-1 from cancer cells." (PMID 37166517, 2023). "In this study, we also show that a mouse anti-human CHI3L1 polyclonal neutralizing antibody (nCHI3L1 Ab) largely attenuated tumor growth and metastasis in vitro and in vivo using three cancer models including lung, pancreatic and colorectal cancers." (PMID 34987649, 2022). "To improve the diagnostic capacity of serum biomarkers for colorectal cancer (CRC), we introduced three novel indicators, namely, the C-X-C motif chemokine ligand 5 (CXCL5), stanniocalcin 2 (STC2), and chitinase 3 like 1 (CHI3L1) and assessed their performances in the detection of CRC." (PMID 35646113, 2022). "Finally, it should be remarked that RANTES/CCL5 is also known to be induced by chitinases, while CHI3L1 can induce macrophage recruitment by MCP-1 chemotaxis in colorectal cancer and has a role in IL-17A-dependent mechanisms." (PMID 29892291, 2018). "In addition, fecal CHI3L1 levels were much higher in CAC patients compared to other sporadic colorectal cancer patients." (PMID 26431492, 2015). "Low-dose purified CHI3L1 can continuously activate the Wnt/β-catenin pathway and trans-nucleic acid translocation in colon cancer epithelial cells, which has a direct, rather than secondary, effect on inflammation-associated colorectal cancer." (PMID 39068486, 2024). "Lower panel: CHI3L1 leads to an increase in VEGF/VEGFA expression through the activation of the ERK1/2 and Akt pathways, promoting angiogenesis and tumor progression in colorectal cancer." (PMID 38177294, 2024). "In contrast, other studies have reported that fecal CHI3L1 is not a reliable marker of colorectal cancer detection in symptomatic patients in primary care settings." (PMID 40643503, 2025). "Several studies have demonstrated that serum CHI3L1 levels and its expression in tumor tissues are significantly elevated in colorectal cancer compared to colitis without cancer." (PMID 40643503, 2025). "While drugs targeting EGFR and VEGFA have been extensively studied for colorectal cancer, there are currently no reported drugs for this disease targeting CHI3L1." (PMID 38177294, 2024). "Several pro-angiogenic (VEGF, Ang-2, PIGF, sVCAM-1, MCP-1, MMP-3, CHI3L1, IL-8 and CXCL16) and ECM-degrading (MMP-2 and MMP-7) proteins are known to be elevated after colorectal cancer resection, but in relation to postoperative complications such research remain scarce." (PMID 39167197, 2024). "In colorectal cancer (CRC), there is a significant expression of CHI3L1 in serum." (PMID 38003338, 2023). "In addition, Chitinase 3-like 1 (CHI3L1) secreted by CAFs acts on CAFs can increase the secretion of IL-8 and affect the angiogenesis of colorectal cancer tumors." (PMID 37666813, 2023). "Moreover, CHI3L1 exerts direct effects on SW480, a human colorectal cancer cell line, by activating the NF-κB and MAPK pathways, consequently upregulating the expression of pro-inflammatory cytokines/chemokines such as TNFα, IL-8, and CCL2 (C-C motif chemokine ligand 2)." (PMID 38667293, 2024). "Importantly, we detect an increased plasma CHI3L1 concentration that correlates with poorer overall survival in our in-house cohort of non-small cell lung cancer (NSCLC), pancreatic ductal adenocarcinoma (PDAC) and colorectal cancer (CRC) patients." (PMID 34987649, 2022).
colorectal cancer (continued). "The influence of chitinase-3-like protein 1 (YKL-40 or CHI3L1) expression on the immunological properties of the tumor microenvironment, which may affect the effectiveness of immunotherapy, is currently not sufficiently understood in colorectal cancer (CRC)." (PMID 37185706, 2023). "Chitinase 3-like 1 (CHI3L1, alias HCgp39 or YKL-40) is a secreted glycoprotein that is not synthesized physiologically, but in inflammatory and cancerous states, it proved to have an important role in macrophage recruitment and angiogenesis during colorectal cancer formation." (PMID 26208990, 2015).
multiple sclerosis (48 papers, 2010 to 2026). A progressive autoimmune disorder affecting the central nervous system resulting in demyelination. "High levels of CSF Chi3l1 are associated with increased disability, including motor, cognitive, and radiological aspects, in patients with multiple sclerosis." (PMID 39769202, 2024). "Elevated levels of Chitinase-3-like protein-1 (CHI3L1) in cerebrospinal fluid have previously been linked to inflammatory activity and disease progression in multiple sclerosis (MS) patients." (PMID 38062768, 2023). "CHI3L1 has been implicated in the pathogenesis of neurological disorders including psychiatric disease and multiple sclerosis, and as a modulator of neuroinflammation." (PMID 34582452, 2021). "Chitinase 3-like 1 (CHI3L1) is known to play a role as prognostic biomarker in the early stages of multiple sclerosis (MS), and patients with high cerebrospinal fluid CHI3L1 levels have an increased risk for the development of neurological disability." (PMID 32346016, 2020). "CHI3L1 is expressed in astrocytes in the brain tissue of patients with multiple sclerosis, and is associated with reactive gliosis in different neuropathological states, particularly those associated with neuroinflammation." (PMID 32437412, 2020). "Chitinase-3-like protein 1 (CHI3L1) has been implicated in multiple sclerosis (MS) pathology, yet its precise role remains unclear." (PMID 40362399, 2025). "In multiple sclerosis (MS) as a chronic autoimmune neurodegenerative disorder, 8‐week vitamin D3 supplementation was associated with reductions in the neuroinflammatory biomarker Chitinase‐3‐like protein 1 (CHI3L1) and oxidative stress markers, while suggesting enhancement of antioxidant capacity." (PMID 41277171, 2025). "Many studies have shown that Chi3l1 is widely expressed in all regions of the human brain and serves as a diagnostic biomarker and therapeutic target for multiple brain-related inflammatory diseases (e.g., encephalitis, psychosis, multiple sclerosis, and brain injury)." (PMID 39769202, 2024). "CHI3L1 is also significantly expressed by macrophages in various inflammatory conditions, including encephalitis, stroke, multiple sclerosis, and brain tumors." (PMID 39827337, 2025). "Beyond multiple sclerosis, Nf-L and CHI3L1 have emerged as important biomarkers in various neurological disorders." (PMID 40564113, 2025). "Elevated expression of CHI3L1 has been observed in a range of neurological disorders, including AD, amyotrophic lateral sclerosis, multiple sclerosis, and schizophrenia." (PMID 41573517, 2025). "Several preclinical studies have investigated the effects of CHI3L1(YKL40) in experimental models of multiple sclerosis, such as animal models of autoimmune encephalomyelitis (EAE), which mimic certain aspects of human multiple sclerosis." (PMID 38543093, 2024). "Elevated levels of CHI3L1(YKL40) have been observed in the cerebrospinal fluid and blood of multiple sclerosis patients, particularly during active disease phases." (PMID 38543093, 2024). "Eight markers were found to be significantly differently expressed in CSF of multiple sclerosis versus control cases: chitinase-3-like-1, soluble CD27 (sCD27), neurofilament light, osteopontin, C5, iC3b, C9 and TCC." (PMID 38368354, 2024). "A study by Semra and colleagues in 2003 compared the performance of ELISA and Western blot for measuring CSF CHI3L1 levels in patients with multiple sclerosis." (PMID 36988727, 2023). "Escalation should be done in RRMS patients with high levels of CSF CHI3L1 before reaching cut off point level, to protect multiple sclerosis patient from further progression and disability." (PMID 36988727, 2023). "Based on the available evidence, it can be concluded that CHI3L1 is a promising biomarker of disease progression in multiple sclerosis (MS)." (PMID 36988727, 2023).
multiple sclerosis (continued). "For example, a study by Disanto and colleagues in 2017 that compared the performance of ELISA and SIMOA for measuring CSF CHI3L1 levels in patients with multiple sclerosis." (PMID 36988727, 2023). "In multiple sclerosis (MS), CHI3L1 levels have been found to be influenced by disease severity, activity, and progression." (PMID 36988727, 2023). "CHI3L1 immunoreactivity has been observed in astrocytes, but not microglia and neurons; its expression correlates with GFAP, particularly in acute inflammatory conditions like multiple sclerosis, suggesting that CHI3L1 is indicative of reactive astrocytosis." (PMID 32536900, 2020). "Conversely, CHIT1, CHI3L1, and AMCase stimulation increased the transmigratory capacity of leukocytes from patients with multiple sclerosis." (PMID 32536900, 2020). "ELISA revealed significant elevation of CHI3L1 in the CSF of multiple sclerosis (MS) patients as well as mild elevation with aging." (PMID 20540736, 2010). "Interestingly, recent studies in other autoimmune‐mediated neuroinflammatory disorders, such as neuromyelitis optica and multiple sclerosis, have shed light on the potential role of CHI3L1 in regulating hippocampal neurogenesis and cognitive function." (PMID 41489316, 2026). "Whether CHI3L1(YKL40) can further serve as a therapeutic target for multiple sclerosis requires further research." (PMID 38543093, 2024). "Other proteins including glial marker chitinase-3-like-1, and inflammatory cytokine osteopontin, have also been identified as potential candidates for predicting multiple sclerosis outcomes, and may offer complementary information to neurofilament light." (PMID 38368354, 2024). "Additionally, immunosuppressive treatments such as mitoxantrone and natalizumab play potential roles in multiple sclerosis (MS) therapy by decreasing cerebrospinal fluid (CSF) levels of Chi3l1." (PMID 39769202, 2024). "CHI3L1 plays a role in multiple sclerosis (MS) pathogenesis, both clinically and experimentally." (PMID 38062768, 2023). "In this study we tested CHI3L1 as a marker of multiple sclerosis." (PMID 32437412, 2020). "This study investigated the expression and subcellular localization of chitinase-3-like protein 1 (CHI3L1) in neutrophils and plasma from untreated and dimethyl fumarate (DMF)-treated multiple sclerosis (MS) patients, and healthy controls." (PMID 41828412, 2026). "Background/Objective: Neurofilament light chain (Nf-L), neurofilament heavy chain (Nf-H), and chitinase 3-like 1 (CHI3L1) are cerebrospinal fluid (CSF) biomarkers of neuroaxonal damage and inflammation in multiple sclerosis (MS)." (PMID 40564113, 2025). "They found the combination of chitinase-3-like-1, CXCL10, CXCL12, CXCL13 increased the AUC for predicting conversion to clinically definite multiple sclerosis after first attack above any single biomarker in isolation." (PMID 38368354, 2024). "Several studies have also shown that CIS patients with higher CSF CHI3L1 levels faster convert to clinically definite MS, suggesting that CHI3L1 might be a prognostic biomarker for disease activity and disability progression in the early stages of multiple sclerosis." (PMID 39768177, 2024). "Additionally, Chi3l1 is a prognostic biomarker for clinically isolated syndromes (CISs), showing high expression levels among CIS patients with the conversion to multiple sclerosis compared with those continued as CIS." (PMID 39769202, 2024). "For example, chitinase-3-like protein 1 (CHI3L1), a human paralog of mouse CHIL3, has been widely studied as a biomarker of disease progression and tissue damage in multiple sclerosis, although its functions in the CNS remains unclear." (PMID 36368330, 2022). "One control patient with multiple sclerosis displayed the highest level of CHIT1 (16,456 pg/mL), CHI3L1 (357 ng/mL) and CHI3L2 (36 ng/mL), but not pNFH (355 pg/mL)." (PMID 34359293, 2021).